SLMAP (sarcolemma associated protein)
Description:
Associates with the striatin-interacting phosphatase and kinase (STRIPAK) core complex, forming the extended (SIKE1:SLMAP)STRIPAK complex. The (SIKE1:SLMAP)STRIPAK complex dephosphorylates STK3 leading to the inhibition of Hippo signaling and the control of cell growth. May play a role during myoblast fusion (By similarity).
Synonyms: KIAA1601; SLAP
Tractability: Antibody: its Gene Ontology location is reachable by antibodies, with high confidence; UniProt places it where antibodies can reach, with medium confidence; UniProt predicts a signal peptide or a membrane-spanning region. PROTAC: ubiquitination databases record sites on it; its protein half-life has been measured.
Gene: Protein-coding gene on chromosome 3 (57,755,450 to 57,931,461, forward strand). Ensembl gene ENSG00000163681.
Subcellular location: Cell membrane, sarcolemma; Cytoplasm, myofibril, sarcomere, M line; Cytoplasm, myofibril, sarcomere, Z line; Cytoplasm, cytoskeleton, microtubule organizing center, centrosome; Endoplasmic reticulum membrane (Isoform 1); Mitochondrion membrane; Endoplasmic reticulum membrane (Isoform 2); Endoplasmic reticulum membrane (Isoform 3); Endoplasmic reticulum membrane (Isoform 4); Endoplasmic reticulum membrane (Isoform 5)
Subcellular location (Human Protein Atlas): Endoplasmic reticulum
Gene Ontology:
Molecular function: protein binding; protein-macromolecule adaptor activity
Biological process: negative regulation of hippo signaling; protein localization to plasma membrane; regulation of membrane depolarization during cardiac muscle cell action potential; regulation of sodium ion transmembrane transport; muscle contraction
Cellular component: cytoplasm; endoplasmic reticulum membrane; FAR/SIN/STRIPAK complex; mitochondrial membrane; plasma membrane; smooth endoplasmic reticulum; centrosome; M band; membrane; sarcolemma; Z disc
Genetic constraint (gnomAD): Loss-of-function variants: 22 observed, 59.11 expected, observed/expected ratio (o/e) 0.37, 90% interval 0.26 to 0.53. The upper end of that interval is the gene's LOEUF score, 0.53, which puts it in group 2 of 6, group 1 being the genes least tolerant of losing a copy. Missense variants: 458 observed, 593.19 expected, observed/expected ratio (o/e) 0.77, 90% interval 0.71 to 0.83. Synonymous variants: 202 observed, 216.82 expected, observed/expected ratio (o/e) 0.93, 90% interval 0.83 to 1.05.
Gene-disease validity (ClinGen):
ClinGen rates the evidence that SLMAP causes each of these diseases.
Brugada syndrome (autosomal dominant): Disputed. A genetically heterogeneous condition characterized by complete or incomplete right bundle branch block accompanied by ST elevation in leads V1-V3.
Brugada syndrome (autosomal dominant): Refuted.
Homologues: Orthologues: pig SLMAP (98% identical), macaque SLMAP (97% identical), dog SLMAP (96% identical), chimpanzee SLMAP (95% identical), rabbit SLMAP (95% identical), guinea pig SLMAP (94% identical), mouse Slmap (92% identical), rat Slmap (89% identical), tropical clawed frog slmap (69% identical), zebrafish slmapa (65% identical). Paralogues in human: CCDC136 (15% identical), TRAF3IP3 (10% identical).
Diseases named in the same sentence as SLMAP in open-access papers:
SLMAP is named in the same sentence as 28 diseases in open-access papers, as found by Europe PMC text mining. Sharing a sentence is not in itself a finding about the gene and the disease. The quoted sentences say what the papers report.
Brugada syndrome (7 papers, 2013 to 2024). "SLMAP mutations have been described in Brugada syndrome (BrS), which results in impairment of the Nav1.5 trafficking, culminating in decreased peak INa density." (PMID 39355352, 2024). "Mutations in SLMAP have been linked to Brugada syndrome with putative deficits in trafficking of the sodium channel Nav1.5 to the cellular membrane." (PMID 39041002, 2024). "SLMAP has also been associated with the development of Brugada syndrome, a cardiac channelopathy, through the silencing of SLMAP by small-interfering RNA (siRNA)." (PMID 38136997, 2023). "Mutations in human SLMAP have been linked to Brugada syndrome with putative deficits in trafficking of the sodium channel (Nav1.5) to the cell membrane resulting in aberrant electrical activity and heart function." (PMID 30934005, 2019). "In this regard, mutations in the sarcolemmal membrane-associated protein (SLMAP) were linked to Brugada syndrome with associated deficits in Nav1.5 activity in a Japanese population." (PMID 30934005, 2019). "Mutations in human SLMAP have been shown to lead to Brugada syndrome due to potential defective trafficking of the alpha 1 subunit (Nav1.5) of the sodium channel to the sarcolemma although this needs to be confirmed." (PMID 30934005, 2019). "Recently, SLMAP was reported to be involved in regulating glucose uptake in type 2 diabetes, and modulating intracellular trafficking of hNav1.5 channel in Brugada syndrome." (PMID 24019967, 2013).
diabetes (5 papers, 2011 to 2023). "SLMAP has been implicated in vascular endothelial dysfunction in diabetes, potentially leading to DH." (PMID 36977298, 2023). "The role of SLMAP genetic variants in the susceptibility to diabetes and diabetic retinopathy in the Qatari population has been reported." (PMID 32587868, 2020). "Aberrant expression of SLMAP was noted in animal models of diabetes and endothelial dysfunction while genetic variants were recently defined in diabetic retinopathy in humans and mutations in SLMAP were linked to Brugada patients." (PMID 30934005, 2019). "In the present study we have explored the genetic association of SLMAP gene polymorphisms [SLMAP rs17058639 C > T, rs1043045 C > T and rs1057719 A > G] in the Qatari population, which has one of the highest incidence of diabetes worldwide." (PMID 25880194, 2015). "Overexpression of SLMAP gene has been associated with diabetes and endothelial dysfunction of macro- and micro-blood vessels." (PMID 25880194, 2015). "The present data linking dysregulation of SLMAP expression to GLUT-4 in adipocytes from Tally Ho mice reinforces our conclusion that a dysregulation of SLMAP expression is linked, in a tissue-specific manner, to diabetes." (PMID 21785580, 2011). "Thus, SLMAP may be an important regulator of glucose uptake or involved in GLUT-4 fusion/translocation into the plasma membrane of mouse abdominal adipose tissue and changes in SLMAP expression are linked to hyperglycemia and diabetes." (PMID 21785580, 2011). "Overexpression of SLMAP correlates with endothelial dysfunction in the microvasculature of diabetic db/db mice, and several other studies have suggested the role of SLMAP in diabetes and other macro/micro vascular diseases." (PMID 25880194, 2015). "SLMAP has a role in vascular endothelial dysfunction and may be a marker of microvascular dysfunction in diabetes." (PMID 36977298, 2023). "The role of SLMAP gene polymorphisms in susceptibility of diabetes (with or without retinopathy) has not been explored." (PMID 25880194, 2015). "However, the association between GLUT-4 and SLMAP was decreased in the diabetic mice when compared to the NG controls, perhaps reflecting that changes in SLMAP expression play a compensatory role in diabetes." (PMID 21785580, 2011). "The altered association of GLUT-4 and SLMAP in the hyperglycemic state suggests that alterations in the regulation of SLMAP expression might play an important role in the development of diabetes." (PMID 21785580, 2011). "Collectively these data suggest that SLMAP is involved in GLUT-4 regulation in adipose tissue and abnormalities in the regulation of SLMAP expression in adipose tissue from diabetic Tally Ho mice may be linked to alterations in glucose transport and the etiology of diabetes in this animal." (PMID 21785580, 2011).
endothelial dysfunction (4 papers, 2011 to 2024). In vascular diseases, endothelial dysfunction is a systemic pathological state of the endothelium (the inner lining of blood vessels) and can be broadly defined as an imbalance between vasodilating and vasoconstricting substances produced by (or acting on) the endothelium. "We have reported previously that endothelial dysfunction in db/db mice is associated with a significant upregulation of the expression of the tail-anchored membrane protein, SLMAP." (PMID 21785580, 2011). "Furthermore, treatment with the PPARγ agonist, COOH, reversed the endothelial dysfunction in db/db mice and corrected the aberrant expression of vascular SLMAP." (PMID 21785580, 2011).
diabetic retinopathy (3 papers, 2015 to 2020). "In this study our primary objective is to explore the role of SLMAP gene polymorphisms in the susceptibility of type 2 diabetes (T2DM) with or without diabetic retinopathy (DR) in the Qatari population." (PMID 25880194, 2015).
type 2 diabetes (3 papers, 2011 to 2015). "Firstly, in abdominal adipocytes from the Tally Ho mouse, a polygenic model of type 2 diabetes, there was an upregulation of the 45 and 35 KDa isoforms of the tail-anchored membrane protein SLMAP in HG mice." (PMID 21785580, 2011). "In the current study we have further pursued the link between SLMAP expression and type 2 diabetes by utilizing the polygenic type 2 diabetic Tally Ho mouse model." (PMID 21785580, 2011). "Our previous studies with db/db mice shown that a deregulation of SLMAP expression plays an important role in type 2 diabetes." (PMID 21785580, 2011).
diabetic macular edema (1 paper, 2015). "We performed “trend analysis” and found a significant trend of association between SLMAP rs17058639 CC genotype and diabetic macular edema (DME) suggesting a role as a prognostic marker for DR in T2DM patients." (PMID 25880194, 2015).
dilated cardiomyopathy (1 paper, 2022). Cardiomyopathy which is characterized by dilation and contractile dysfunction of the left and right ventricles. "SLMAP can also inhibit Hippo signaling; a DMR enriched pathway at 1.5 months was previously associated with dilated cardiomyopathy and ischemic heart disease." (PMID 36555856, 2022).
Duchenne muscular dystrophy (1 paper, 2025). Duchenne muscular dystrophy (DMD) is a neuromuscular disease characterized by rapidly progressive muscle weakness and wasting due to degeneration of skeletal, smooth and cardiac muscle. "Duchenne muscular dystrophy is a genetic disease where loss of sarcolemma-associated protein, dystrophin, leads to progressive muscle wasting, and eventual loss of life from complications linked to cardiac deficits." (PMID 40970088, 2025).
epithelioid mesothelioma (1 paper, 2022). "Notably, AX10‐positive sarcomatoid mesothelioma tissues also stained with a commercially available antibody against SLMAP, whereas AX10‐negative epithelioid mesothelioma tissues did not stain with a commercially available antibody against SLMAP." (PMID 35916358, 2022).
heart failure (1 paper, 2024). Inability of the heart to pump blood at an adequate rate to meet tissue metabolic requirements. "Additionally, CSRP3 and SLMAP that were identified as possibly downregulated are known calcium handling modulators and are dysregulated in heart failure, with downregulation of CSRP3 in a Ryr2 KO mouse model." (PMID 39041002, 2024).
Hyperglycemia (1 paper, 2011). An increased concentration of glucose in the blood. "Further studies are required to test if alterations of SLMAP phosphorylation and glycosylation in hyperglycemia may cause malfunction and mislocalization of SLMAP that leads to alteration of GLUT-4 and regulation of glucose transportation." (PMID 21785580, 2011). "It is noteworthy that SLMAP upregulation was unaltered in the myocardium from these animals suggesting that changes in SLMAP regulation are not simply a secondary response to the diabetic state, that is, hyperglycemia." (PMID 21785580, 2011). "The Tally Ho mice investigated in the current study although hyperglycemic did not have elevated insulin levels thus suggesting that expression of SLMAP is affected by hyperglycemia and not insulin." (PMID 21785580, 2011).
ischemic heart diseases (1 paper, 2022). "Interestingly, decreased SLMAP protein levels were also observed in cardiac tissues of Mayak workers diagnosed with ischemic heart diseases after occupational exposure to >500 mGy external gamma rays, which further supports the possible involvement of SLMAP in RICVD." (PMID 36555856, 2022).
lung adenocarcinoma (1 paper, 2023). A carcinoma that arises from the lung and is characterized by the presence of malignant glandular epithelial cells. "In addition to STRN-ALK fusion, ALK gene rearrangements may also lead to novel fusion of ALK and SLMAP genes, making SLMAP a potential marker for treating lung adenocarcinoma." (PMID 38201504, 2023).
mesothelioma (1 paper, 2022). A usually malignant and aggressive neoplasm of the mesothelium which is often associated with exposure to asbestos. "Our results indicated that a unique epitope of sarcolemma‐associated protein (also known as sarcolemmal membrane‐associated protein, SLMAP) could be a novel therapeutic target for patients with mesothelioma." (PMID 35916358, 2022). "We hypothesize that AX10 may recognize a unique epitope on an alternatively spliced form of SLMAP that is preferentially expressed in sarcomatoid mesothelioma cells and several other malignant tumors." (PMID 35916358, 2022). "Since the functional diversity of SLMAP is thought to be dependent on alternative splicing, the SLMAP isoform recognized by AX10 may contribute to tumorigenesis, including that of mesothelioma." (PMID 35916358, 2022).
prediabetes (1 paper, 2024). "Additionally, our study has shown lower expression of a member of the tail-anchored membrane proteins superfamily, Sarcolemmal membrane-associated protein (SLMAP), in the prediabetes group compared to normoglycemic individuals." (PMID 39085321, 2024).
sarcoma (1 paper, 2022). A usually aggressive malignant neoplasm of the soft tissue or bone. "SLMAP is known to be overexpressed in sarcoma, although it is not known which splicing form of SLMAP is overexpressed." (PMID 35916358, 2022).
soft tissue sarcoma (1 paper, 2020). A malignant neoplasm arising from muscle tissue, adipose tissue, blood vessels, fibrous tissue, or other supportive tissues excluding the bones. "In a previous study, RAF1 fusions were reported in soft tissue sarcoma, in which the fusion counterparts, PDZRN3, SLMAP and TMF1, were identified in three of eight cases." (PMID 32825119, 2020).
cancer (5 papers, 2013 to 2023). A tumor composed of atypical neoplastic, often pleomorphic cells that invade other tissues. "Cancer-related splice variants in SLMAP and CETN3 were validated by regulation of SRSF2 at the molecular level." (PMID 36623729, 2023). "SRSF2 regulated cancer-related SLMAP and CETN3 to generate different splice variants with distinct functions in cancer." (PMID 36623729, 2023). "Moreover, it was demonstrated that depletion of SLMAP results in the constitutive activation of the Hippo Pathway, whose disruption was associated with tumorigenesis, cancer progression and tumor immunogenicity." (PMID 30837581, 2019). "According to literature data, IGJ and SLMAP seemed to be the most relevant in human cancer, and they were selected to validate the differential gene expression by IHC on an independent cohort, including 30 PSC, 31 LUAD and 31 LUSC cases." (PMID 30837581, 2019). "In our work, sCAR-PPAb enhanced phagocytosis of K562/ADR cells by macrophages through binding with SLMAP on K562/ADR, indicating an interaction between drug resistant cancer cells and macrophages, as well as a role of SLMAP in mediating the interaction." (PMID 24019967, 2013). "However, to date, SLMAP has not been linked to cancer drug resistance and macrophage phagocytosis." (PMID 24019967, 2013).
tumor (4 papers, 2017 to 2023). "In this study, the elevated inclusion of SLMAP exon 24 and reduced inclusion of CETN3 exon 5 were observed in CRC tumor samples." (PMID 36623729, 2023).
retinopathy (1 paper, 2020). "Others have looked specifically at the SLMAP gene in the Qatari population and found that the SLMAP C>T polymorphism is associated, as an independent risk factor for retinopathy." (PMID 32587868, 2020).
SLMAP also shares sentences with these, for which no sentence is quoted: breast cancer (2 papers); cardiomyopathies (1); colon cancer (1); genetic disease (1); glioma (1); leiomyosarcoma (1); neuroblastoma (1); Obesity (1).